KEAP1 (kelch like ECH associated protein 1)
Diseases named in the same sentence as KEAP1 in open-access papers (continued):
Sharing a sentence is not in itself a finding about the gene and the disease.
tumor (continued). "Accordingly, the stable knockdown of KEAP1 was also found to enhance while NRF2 silencing repressed the expression of TKT in HCC cells, wherein this enzyme promoted NADPH synthesis, tumor growth, metastasis formation and sorafenib resistance." (PMID 32443774, 2020). "The tumour suppressor miR-153-3p directly binds to the 3′ UTR of NRF2 inhibiting its expression, and miR-432-3p downregulates KEAP1 expression by directly targeting the coding region." (PMID 33276631, 2020). "High levels of methylation of the KEAP1 gene promoter have been observed in human CRC cell lines and tumour samples, leading to lower levels of KEAP1 mRNA, increased NRF2 protein and over-expression of its target genes." (PMID 33276631, 2020). "KEAP1 regulates the cytoprotection induced by NRF2 and has been reported to be a candidate tumor suppressor." (PMID 32327612, 2020). "Indeed, analysis of two FH-deficient cell lines—UOK 262 and NCCFH1—as well as FH-deficient tumor, showed strong succination of various, functionally important proteins, including glyceraldehyde 3-phosphate dehydrogenase (GAPDH) and Kelch-like ECH-associated protein 1 (Keap1)." (PMID 31963199, 2020). "The synergy between the KEAP1/NRF2 and PI3K pathways drives NSCLC with an altered immune microenvironment and achieves tumour regression through suppression of immune checkpoint." (PMID 33186371, 2020). "Redox tumours are enriched for oxidation-reduction and glutathione pathways and harbor more NFE2L2/KEAP1 alterations and copy gain in the 3q2 locus." (PMID 31395880, 2019). "Seemingly contradictory, various previous studies on tumor cell lines or murine DCs showed that SFN enhanced the cellular antioxidant capacity by increasing KEAP1/NRF2/ARE-dependent expression of phase II antioxidant enzymes, e.g., HO-1." (PMID 30487791, 2018). "Concomitant deletion of NRF2 in KEAP1-KO tumors did not significantly change or moderately reduced tumor growth." (PMID 41035689, 2025). "There was a 13.8% increase in immunosuppressive FoxP3+ CD4+ T cells as a total percentage of T cells in KEAP1 KO versus WT tumors; however, we did not detect a difference in the activation state of anti-tumor CD8+ T cells or NK cells." (PMID 41462606, 2025). "Both CDDO-Me and omaveloxolone reduced the tumor burden and improved immune cell phenotypes within the TIME independent of KEAP1 mutational status." (PMID 41462606, 2025). "STK11 and KEAP1 mutations are also not reliable predictors of response to ICI therapy, given their association with a non-inflamed tumor microenvironment (TME) and frequent co-occurrence with mutations such as KRAS." (PMID 40535117, 2025). "Given that the KEAP1/NRF2 antioxidant signaling pathway regulates ROS and iron metabolism-related genes and is a key negative regulator of ferroptosis in tumor cells, we hypothesized that TMEM160 regulates ferroptosis in GC cells via the KEAP1/NRF2 pathway." (PMID 40223081, 2025). "We performed RNA-seq studies using WT, KEAP1-KO, and DKO tumor tissues." (PMID 41035689, 2025). "Higher magnification images clearly showed that, while NQO1 expression in both tumor and stroma areas was very low in the WT tumor tissues, a high level of NQO1 expression was detected in the tumor area but not in the stroma area of the KEAP1-KO tumor tissues." (PMID 41035689, 2025). "We demonstrated the transition of PTC to SCC, in which tumor cells carried none of the common driver mutations (e.g. BRAF or RAS), but showed biallelic inactivation of KEAP1, STK11, and RB1." (PMID 40600748, 2025). "Evaluating co-occurring mutations depending on PD-L1 status, in PD-L1 negative tumours, KRAS/STK11 mutation was detected in 10% and STK11/KEAP1 mutation in 6% of cases, which was consistent with previous clinical study results." (PMID 40650126, 2025).
tumor (continued). "Moreover, high TMB was associated with increased T cell infiltration and exhibited a distinct gene signature, which highlights the potential of IFNG, KEAP1, and PHKG2 as predictive markers for T cell infiltration and the tumor microenvironment status in OV." (PMID 40744688, 2025). "It should be noted that peripheral myeloid cells and neutrophils in KEAP1-KO tumor-bearing mice were not increased (respectively) despite the fact that the KEAP1-KO tumors show a comparable size with WT tumors." (PMID 41035689, 2025). "Other somatic mutations associated with VTE independent of tumor type include KRAS, STK11, MET, KEAP1, CTNNB1, and CDKN2B." (PMID 39851266, 2025). "While M-MDSC cells appeared to be increased in WT tumor-bearing mice compared with non-tumor-baring mice, the suppressive cells were not increased in KEAP1-KO tumor-bearing mice." (PMID 41035689, 2025). "Activation of the KEAP1/NRF2 axis and regulation of inflammatory cytokines suggest that TROX may act at multiple levels, interfering with mechanisms that contribute to tumour progression and chemoresistance." (PMID 41042696, 2025). "In addition, NR0B1, an orphan nuclear receptor expressed in KEAP1-mutant NSCLC, has been identified as potential druggable target, while tumours with overactivation of NRF2 show selective vulnerability to inhibitors of respiratory complex I." (PMID 40849356, 2025). "We previously showed that CD8 T cell depletion had no impact on Keap1 mutant tumor growth using this model." (PMID 38536921, 2024). "Our preliminary data provide new insights about the downstream effects of KEAP1 dysfunction on NRF2 and NOTCH deregulation in this type of tumor and corroborate the hypothesis of a cooperation of these two pathways in the tumorigenesis of SCLC." (PMID 38791966, 2024). "Patients with KEAP1 mutant LUAD are known to have poor responses to checkpoint blockade, and our previous work has similarly demonstrated that this also holds true in our Keap1 mutant orthotopic tumor mouse model." (PMID 38536921, 2024). "Whole exome sequencing (WES) identified a KEAP1/STK11 co-mutation with loss of function for both genes, a MAP2K1 activation, and an ARID2 loss of function, as well as a low tumor mutational burden (TMB) with no actionable mutation (4.4 mut/Mb)." (PMID 39170614, 2024). "We treated mice with Keap1 R470C mutant lung tumors with DRP-104 and/or anti-PD1 and harvested whole lungs for single-cell analysis after 5 days of treatment, a time point where tumor burden differences among treatment arms are minimal." (PMID 38536921, 2024). "NSCLC patients with KRAS and STK11 co-mutations are also more likely to carry the mutations in KEAP1 and ATM genes and are predisposed to the development of a cold tumor (without immune cells in tumor microenvironment)." (PMID 37509393, 2023). "Tumor intrinsic pathways including STK11/LKB1 and KEAP1 are associated with non-T cell-inflamed tumor microenvironment (TME), which is also called a “cold” tumor, thus impairing the clinical efficacy of immunotherapy." (PMID 37265800, 2023). "We again find that KEAP1 mRNA expression displays a striking degree of heterogeneity and a distinctly bimodal distribution, with some single tumor cells having abundant reads and others completely lacking in KEAP1 expression." (PMID 36864091, 2023). "The cell cycle results showed that Keap1−/− cells underwent a cycle arrest at the G1 phase, which is contributable to tumour reduction, but no significant changes in the Keap1β cell cycle were observed." (PMID 36142252, 2022). "In contrast, smaller tumor sizes and lighter tumor weights were observed in HCT116-OE-LINC00239-Keap1 and HCT116-OE-LINC00239-sgNrf2#1 cells, further confirming that Keap1/Nrf2 signaling is involved in the ferroptosis-suppressing activity of LINC00239 in CRC development." (PMID 36038548, 2022).
tumor (continued). "Staining of 4-hydroxy-2-noneal (4-HNE), a lipid peroxidation marker, in these tumor samples revealed that KEAP1 deletion decreased 4-HNE staining, which was normalized by FSP1 deletion in KEAP1 deficient tumors." (PMID 35459868, 2022). "Moreover, we confirmed that XN binds to KEAP1, which has a cysteine residue-rich gene, affects NRF2 activation, and controls tumor progression." (PMID 36615756, 2022). "In addition, the interaction between Keap1 and Nrf2 was found to suppress LUAD tumor progression by inhibiting the S100P protein." (PMID 36177001, 2022). "The results obtained from Keap1−/− and Keap1β(Keap1Δ1–31) cells unraveled that PTEN was obviously upregulated, whilst PI3K, AKT1, and mTOR were all downregulated, showing the similar trends to those of in vivo growing tumours." (PMID 36142252, 2022). "The immunohistochemistry results showed that in the subcutaneous tumor tissues of nude mice inoculated with primary A2058 cells, the expression of PCK1 in the vemurafenib group was up-regulated compared with the DMSO group, while KEAP1 was inhibited." (PMID 36700470, 2022). "Decreased Keap1 by TRIM25 activates Nrf2 and leads to tumor cell proliferation." (PMID 36552825, 2022). "Thus, based on these data, it appears that there is a fine-tuning between KEAP1 and NRF2 levels and this determines which effect of this pathway will be more prominent under specific circumstances of a certain type of tumor." (PMID 33808001, 2021). "Taken together, our results found circKEAP1 could serve as a sponge for miR-141-3p to regulate KEAP1 and activate the KEAP1/NRF2/HDAC4 signal pathway via the ceRNA mechanism to repress tumor growth." (PMID 34136401, 2021). "We also verified that the changes of KEAP1 and NRF2 were corresponded with TRPM2 KO in tumor cells." (PMID 34226519, 2021). "But the expression of Keap1 was independent of age, gender, smoking history, tumor location, degree of differentiation and tumor maximum diameter." (PMID 34466284, 2021). "Keap1 was lowly expressed in tumor tissues compared to matched non-cancerous tissues, and its expression was correlated with TNM stage and lymph node metastasis." (PMID 34466284, 2021). "Elevated KEAP1 could inhibit the expression of NRF2 and HDAC4, and then abolish the suppression of HDAC4 for the tumor suppressor miRNAs miR-1 and miR-206, which result to repress the cell proliferation." (PMID 34136401, 2021). "The link between NRF2 and immune-evasive features is also found in KEAP1-mutated LUAD, thus showing that this tumor-promoting function of NRF2 is not restricted to a single tumor entity." (PMID 32978520, 2020). "Despite activating hotspots in NFE2L2 and inactivating mutations in its negative regulators, KEAP1, CUL3, and SIRT1 have been reported, they do not justify themselves the overexpression of NRF2 transcriptional signature in the different tumor types." (PMID 33233657, 2020). "Given that NRF2 protein translocates into the nucleus to activate the transcription of downstream target genesin the KEAP1/NRF2 pathway, we further examined the protein expression of nuclear NRF2 and the downstream target HO-1 in these tumor cells by western blot analysis." (PMID 32576270, 2020). "Finally, the metabolic outputs of KEAP1 modification that are NRF2-independent are completely unexplored and have the potential to contribute to both normal and tumor metabolism." (PMID 33080927, 2020).
tumor (continued). "Thus, PPI network analysis suggested that cross-talk of KEAP1 and NRF2 with the 9-gene potential signature coordinately drives tumor progression and therapeutic resistance in LUAD." (PMID 32327612, 2020). "The concordance between methylation levels and protein expression was also investigated by immunohistochemical analysis in 11 tumor cases showing KEAP1 promoter methylation (3 AC and 8 TC) and 3 TCs without methylation." (PMID 31126053, 2019). "Genetic deletion of Keap1 or overexpression of its target, the anti-oxidant master regulatory transcription factor NRF2, accelerates KRas-driven LuAd in mice, suggesting that excessive oxidative stress limits tumour progression." (PMID 31032816, 2019). "Thus, PPI network analysis suggested that the cross-talk of KEAP1, NRF2, and CUL3 with the 17-gene signature coordinately drives tumor progression and therapeutic resistance in HNSCC." (PMID 29306329, 2018). "Although epigenetic modification affects the expression of Nrf2 and Keap1 in many ways, their mRNA levels are not different between the tumor and normal tissues." (PMID 27999449, 2016). "This signature, while generally segregating with NRF2/KEAP1 genotype in cultured cells (i.e., higher expression in mutant cells), did not appear to do so in lung SCC, as high levels of AKR were detected in tumours without these mutations." (PMID 27824809, 2016). "In the absence of detectable Bach1 mRNA expression, the mRNA levels of Keap1, but not Nrf2, retained significant correlation with that of Hmox1 in the tumor tissue of CRC." (PMID 27999449, 2016). "Therefore, in order to evaluate the effect of RTA 405, we first conducted a series of experiments to characterize the status of KEAP1 and NRF2 in a panel of twenty human tumor lines." (PMID 26301506, 2015). "In contrast to the loss of KEAP1 in MEFs, loss of functional KEAP1 and high basal NRF2 activity in human tumor cell lines was not correlated with a significant increase in growth." (PMID 26301506, 2015). "Taken together, the potential implications of DNA-level alterations affecting components of the CUL3/KEAP1/RBX1 protein complex are broad and, cumulatively, may have profound implications in tumor biology." (PMID 25114896, 2014). "Importantly, in vitro, isogenic loss of KEAP1 does not result in decreased sensitivity to G12Ci, which suggests that the resistance observed in patients is not cell intrinsic, and thus may be mediated by a change in the tumour microenvironment which is absent in the cell culture setting." (PMID 40890297, 2025). "The Keap1/Nrf2/ARE signaling pathway plays a vital role in protecting cells against endogenous and exogenous stresses, such as oxidative stress and xenobiotics, which can increase the antioxidant capacity of tumor cells by eliminating ROS and relieve the level of ER stress." (PMID 40735463, 2025). "Further immunohistochemical analyses revealed that F4/80-positive macrophages and MPO-positive neutrophils were decreased in KEAP1-KO tumors compared with WT tumors, although their spatial distribution within the tumor tissue was not affected by the KEAP1 deletion." (PMID 41035689, 2025). "Additionally, the expression levels of Keap1, HO-1, and Nrf2 proteins are elevated, suggesting that LBP may enhance anti-tumor efficacy by activating the Keap1/Nrf2 pathway and boosting immune responses." (PMID 41050703, 2025). "By activating the Keap1/Nrf2 signaling pathway, NCI-H835 cells effectively mitigated the production of ROS and the consequent DNA damage that AXI could potentially induce, as observed in other tumor cell lines." (PMID 39050569, 2024).
tumor (continued). "Finally, the subcutaneous tumor formation experiments in nude mice were conducted using the H1975 KEAP1-knockdown cells with or without ASNS overexpression treated with vehicle or MLN8237." (PMID 38521813, 2024). "In addition, in the absence of ADAR1, Keap1 expression was increased, and Nrf2 expression was attenuated in mouse tumor tissues." (PMID 38468359, 2024). "Therefore, MCL stabilized the antioxidant regulatory protein NRF2 by directly binding to KEAP1 and promoting its nuclear translocation, thereby attenuating oxidative stress in MCF7TAMR cells, and ultimately suppressing tumour proliferation through the ROS/pAKT/ASAH1 pathway." (PMID 38924190, 2024). "This review mainly focuses on the Keap1/Nrf2/ARE signaling pathway and its downstream genes, as well as the expression of related signaling pathways involving AKT/AMPK, PI3K/AKT/mTOR and NF-ĸB, and so on, thereby affecting the malignant biological behavior of tumor cells." (PMID 37810967, 2023). "Currently, there is a controversy regarding whether KEAP1 and DPP7 can act as tumor suppressors." (PMID 37781518, 2023). "Tumor cell immunohistochemical PD-L1, plasma soluble PD-L1 (sPD-L1), TMB/blood TMB (bTMB), mismatch repair defect (dMMR)/microsatellite instability-high (MSI-H), and other biomarkers such as KRAS, STK11, KEAP1, and DNA damage response (DDR) gene variation are potential biomarkers." (PMID 36406130, 2022). "Consistent with baseline differences in cell growth, Keap1 expressing clones showed poorer tumorsphere formation after cisplatin treatment with clear contrast in parental and control cells, suggesting additional evidence of therapeutic resistance in HNSCC through self-renewal of the tumor cells." (PMID 35945195, 2022). "Taken together, our data show that, in the H1299 xenograft model, FSP1 is required (but probably not sufficient) for KEAP1 inactivation-induced tumor growth, and further suggest that FSP1 promotes KEAP1 deficient lung tumor growth likely through suppressing lipid peroxidation and ferroptosis." (PMID 35459868, 2022). "These investigations about immune infiltration and tumor environment indicated that the Wild group patients might have a higher immunotherapy response rate due to the TME status and the KEAP1/NFE2L2/CUL3 alterations that contribute to the tumor immune escape and “cold” tumor's formation." (PMID 34617407, 2021). "Several miRs that exhibit altered expression in ESCC are able to regulate the activity of either NRF2 or KEAP1, and may provide an alternative route by which the expression of NRF2-target genes can be enhanced in ESCC tumours lacking NFE2L2 mutations." (PMID 33276631, 2020). "In exercised tumor hosts, the levels of Nrf2 and Keap1 as well as their ratio did not change." (PMID 30823492, 2019). "Without Bach1 expression, Keap1 may become the major regulator of Hmox1 mRNA transcription in CRC tumor tissue." (PMID 27999449, 2016). "Interestingly, we did not observe DNA sequence mutations in the NFE2L2 or KEAP1 genes in OVCA, even though this mechanism of NRF2 activation is well established in many tumor types." (PMID 25114896, 2014). "Unlike EGFR‐mutant tumours, which exhibit relatively uniform biology and high therapeutic sensitivity, KRAS‐mutant NSCLC is characterised by profound molecular heterogeneity, divergent co‐mutational profiles (e.g., STK11, KEAP1), and dynamic crosstalk with the tumour microenvironment (TME)." (PMID 41025426, 2025). "Third, the increased density of neutrophils in the tumour immune microenvironment in LUADs with mutant KEAP1 was closely related to worse OS, which means neutrophils may play a more critical role in the prognosis of LUAD patients with mutant KEAP1 than T and B lymphocytes." (PMID 38962454, 2024). "Notably, although, one tumor had absent Keap1 transcript expression (HNSCC-17, oral cavity, Suppl." (PMID 35945195, 2022).